DECR2 (2,4-dienoyl-CoA reductase 2)
Description:
Auxiliary enzyme of beta-oxidation. Participates in the degradation of unsaturated fatty enoyl-CoA esters having double bonds in both even- and odd-numbered positions in peroxisome. Catalyzes the NADP-dependent reduction of 2,4-dienoyl-CoA to yield trans-3-enoyl-CoA. Has activity towards short and medium chain 2,4-dienoyl-CoAs, but also towards 2,4,7,10,13,16,19-docosaheptaenoyl-CoA, suggesting that it does not constitute a rate limiting step in the peroxisomal degradation of docosahexaenoic acid.
Synonyms: pDCR; SDR17C1
Tractability: Small molecule: a structure with a bound ligand is known. PROTAC: ubiquitination databases record sites on it; its protein half-life has been measured.
Target class: Enzyme; Oxidoreductase
Gene: Protein-coding gene on chromosome 16 (401,854 to 412,492, forward strand). Ensembl gene ENSG00000242612.
Subcellular location: Peroxisome
Subcellular location (Human Protein Atlas): Peroxisomes; Microtubules
Pathways (Reactome):
Metabolism: Beta-oxidation of very long chain fatty acids
Protein localization: Peroxisomal protein import
Gene Ontology:
Molecular function: 2,4-dienoyl-CoA reductase (NADPH) activity; protein binding; trans-2-enoyl-CoA reductase (NADPH) activity
Biological process: unsaturated fatty acid biosynthetic process; fatty acid beta-oxidation using acyl-CoA oxidase; fatty acid metabolic process; fatty acid catabolic process
Cellular component: cytosol; peroxisomal membrane; peroxisome
Genetic constraint (gnomAD): Loss-of-function variants: 34 observed, 25.95 expected, observed/expected ratio (o/e) 1.31, 90% interval 1 to 1.73. The synonymous counts are far from expectation, so gnomAD's model fits this gene poorly and the ratio says little. Missense variants: 485 observed, 396.38 expected, observed/expected ratio (o/e) 1.22, 90% interval 1.13 to 1.32. Synonymous variants: 224 observed, 172.37 expected, observed/expected ratio (o/e) 1.3, 90% interval 1.16 to 1.45.
Homologues: Orthologues: chimpanzee DECR2 (99% identical), guinea pig DECR2 (85% identical), rat Decr2 (83% identical), mouse Decr2 (82% identical), pig DECR2 (80% identical), zebrafish decr2 (70% identical), tropical clawed frog decr2 (66% identical), dog DECR2 (63% identical). Paralogues in human: DECR1 (35% identical).
Diseases named in the same sentence as DECR2 in open-access papers:
DECR2 is named in the same sentence as 16 diseases in open-access papers, as found by Europe PMC text mining. Sharing a sentence is not in itself a finding about the gene and the disease. The quoted sentences say what the papers report.
prostate carcinoma (2 papers, 2024 to 2025). A carcinoma that arises from epithelial cells of the prostate gland. "DECR2, a 2,4‐dienoyl‐CoA reductase 2, was reportedly involved in cell proliferation in prostate cancer cell lines, since lentiviral vector‐mediated overexpression intensified cell growth." (PMID 40022573, 2025).
Alzheimer disease (1 paper, 2026). A progressive, neurodegenerative disease characterized by loss of function and death of nerve cells in several areas of the brain leading to loss of cognitive function such as memory and language. "This protein plays a crucial role in the β-oxidation pathway, which is essential for cellular energy production 32 Our study identify DECR2 as a potential therapeutic target for Alzheimer's disease (AD)." (PMID 41399369, 2026).
asthma (1 paper, 2020). "Interestingly, 4 genes of MPI, DECR2, LNPEP, and TTC19 are newly reported to be involved in severe asthma risk." (PMID 33066754, 2020).
cervical cancer (1 paper, 2022). A primary or metastatic malignant neoplasm involving the cervix. "In the present study, the immune subtype-relevant signature (covering TMEM125, TFF1, DECR2, LONRF3, DAPL1, and ANKRD35) was quantified, which predicted cervical cancer recurrence accurately and independently." (PMID 36313466, 2022).
prostate tumours (1 paper, 2024). "Impact of DECR2 and perFAO inhibition via thioridazine was examined in vitro, in vivo, and in clinical prostate tumours cultured ex vivo." (PMID 38216720, 2024).
cancer (3 papers, 2019 to 2025). A tumor composed of atypical neoplastic, often pleomorphic cells that invade other tissues. "Additionally, ACOX3, ACAD9, ACAD10, ACOT1, ACOT8, and DECR2 displayed positive associations with PEBP1/STK11 co-expression across various cancer types, highlighting a potential involvement in enhancing fatty acid metabolism in the context of PEBP1/STK11 expression." (PMID 40806276, 2025). "We applied a hard filter to the GSMs and finally selected six genes (CLDN3, DECR2, EVA1B, NME4, NTSR1 and XPNPEP3) associated with epigenetic regulation, differentiation and cancer (Pearson’s correlation test; p-value ≤ 0.001)." (PMID 31040866, 2019).
tumor (3 papers, 2022 to 2025). "Future work is warranted to explore in detail and dissect the specific roles of DECR2 in these activities and the possibilities that these functional pathways intersect in order to drive tumour progression." (PMID 38216720, 2024). "In contrast, overexpression of DECR2 in LNCaP cells significantly increased tumour growth compared with control cells." (PMID 38216720, 2024). "DECR2 influences cell cycle progression and lipid metabolism to support tumour cell proliferation." (PMID 38216720, 2024). "This suggests that low DECR2 expression may be advantageous to promote tumour growth, which is contradictory to our current findings." (PMID 38216720, 2024). "DECR2 expression was found to be elevated in metastatic CRPC, and its silencing induced cell cycle arrest, reduced tumor growth in vivo, and altered cellular lipid profiles." (PMID 40647540, 2025). "Depletion of DECR2 significantly suppressed proliferation, migration, and 3D growth of a range of CRPC and therapy-resistant PCa cell lines, and inhibited LNCaP tumour growth and proliferation in vivo." (PMID 38216720, 2024).
DECR2 also shares sentences with these, for which no sentence is quoted: colon cancer (1 paper); diabetes (1); Fanconi anemia (1); Immunodeficiency (1); infection (1); liver steatosis (1); neonatal diabetes mellitus (1); non-alcoholic fatty liver disease (1); type 2 diabetes (1).